CDK2 (cyclin dependent kinase 2)
Diseases named in the same sentence as CDK2 in open-access papers (continued):
Sharing a sentence is not in itself a finding about the gene and the disease.
tumor (continued). "Under abnormal conditions, Cyclin E overexpression causes continuous activation of CDK2 and hyperphosphorylation of Rb protein, leading to abnormal cell proliferation and tumor development." (PMID 32862831, 2020). "The encoded protein acts as a tumor suppressor by inhibiting the activity of cyclin-dependent kinase 2 or cyclin-dependent kinase 4 complexes, resulting in cell cycle blocks at G1." (PMID 30651718, 2019). "Concurrently, the levels of G1/S transition‐associated proteins p21, cyclin D1 and CDK2 were also significantly decreased in tumour tissue compared with mice that received vehicle." (PMID 30247801, 2018). "Cyclin Dependent Kinase-2 Associated Protein-1 (CDK2AP1) is known to be a tumor suppressor that plays a role in cell cycle regulation by sequestering monomeric CDK2, and targeting it for proteolysis." (PMID 25785833, 2015). "In comparison to full-length cyclin E (50 kDa), LMW-E forms are uniquely expressed in tumor cells, exhibit enhanced CDK2-associated kinase activity, have increased affinity for CDK2, and exhibit decreased inhibition by CDK2 inhibitors, p21 and p27." (PMID 22479209, 2012). "Haplotype GG in CDK2 was associated with stage II–IV tumours compared to common haplotype AG (OR = 1.73, 95% CI = 1.06–2.82, P = 0.027)." (PMID 23185313, 2012). "For instance, researchers identified that homoharringtonine (HHT) could bind to the PPI site of CDK2, disrupting the interaction between CDK2 and cyclin A, resulting in a loss of CDK2 activity and protein degradation, and preventing tumor progression." (PMID 40657363, 2025). "Aberrant activation of CDK2 is often associated with the uncontrolled proliferation of tumor cells." (PMID 41142018, 2025). "This study specifically focused on the role of FAM50A in tumor proliferation and found that it may be linked to CyclinA2 and CDK2." (PMID 39999107, 2025). "Notably, CDK2 is a clinically relevant druggable liability strongly associated with tumor growth in multiple cancers." (PMID 40180891, 2025). "Furthermore, the complex mediates E2F-dependent transcriptional activation, enabling recognition of both CDK4 and CDK2 substrates, demonstrating dual functional properties associated with cell proliferation and tumor cell transformation." (PMID 41471692, 2025). "On the other hand, a low cytoplasmic CDK2 expression was associated with a high tumour grade (p < 0.0001), triple-negative and HER2-enriched molecular subtypes (p = 0.01), Comedo necrosis (p = 0.002), negative ER status (p = 0.01), and negative PR status (p = 0.002)." (PMID 38732271, 2024). "A high nuclear CDK2 protein expression was significantly associated with aggressive phenotypes, including a high tumour grade, lymph vascular invasion, a poor Nottingham prognostic index (all p-values < 0.0001), and shorter survival (p = 0.006), especially in luminal BC (p = 0.009)." (PMID 38732271, 2024). "CDK2 inhibition phenocopied genetic loss of Mybl2 and significantly reduced tumor growth." (PMID 39113611, 2024). "In tumors with MYCN overexpression, as is the case of NB, interaction with CDK2 appears to be critical for senescence avoidance and immortalization, being associated with worse prognosis and considered a suitable therapeutic target in this tumor type." (PMID 36839989, 2023). "While co-targeting cdk2 and cdk4/6 with endocrine therapy is promising in the pre-clinical setting, most of these approaches are associated with continued tumor proliferation and tumor relapse, and in most cases, failure to respond to treatment can be fatal." (PMID 37049472, 2023).
tumor (continued). "Retinoblastoma protein, a tumor suppressor known for its capability of binding with E2F to inhibit its function, was found to be phosphorylated by CDK2/cyclin E complex, causing the cell cycle progression of an under-developed cell and tumor in the respective bound areas." (PMID 31847444, 2019). "CDK2-associated protein 1 (CDKA1) is a tumor suppressor and an inhibitor of CDK2." (PMID 31803618, 2019). "The present findings reveal that resistance development towards the mTOR-inhibitor, everolimus, is associated with undesired feedback loops, including activation of the Akt/mTOR signaling pathway and increased cdk2/cyclin A expression, and is associated with cell cycle progression and tumor growth." (PMID 24935000, 2014). "The CCNE1 amplification identified in Patient #1′s tumor by FoundationOne next-generation sequencing is important in that it encodes the cyclin E1 protein (which regulates G1 to S phase transition) via binding to and activating cyclin-dependent protein kinase 2 (cdk2)." (PMID 26510912, 2015). "These concerns have been fuelled by RNA interference and knockout mice studies, indicating that functional redundancy may exist between different Cdks, with the loss of Cdk2 alone failing to inhibit tumour cell proliferation, and the loss of both Cdk4 and Cdk6 not preventing cell cycling." (PMID 17179992, 2007). "This study establishes that GR exerts anti-tumor effects in CC HeLa cells by targeting CDK2, potentially via the novel CYP4A22-AS1/LINC00958–hsa-miR-133b–CDK2 regulatory axis." (PMID 41614894, 2026). "IL-6 and B-cell lymphoma 2 showed downregulated expression in tumor tissues, while cyclin-dependent kinase 1, cyclin-dependent kinase 2, cyclin B1, Erb-B2 receptor tyrosine kinase 2, and cyclin B2 were upregulated." (PMID 41650055, 2026). "Anaplastic thyroid carcinoma (ATC), the most lethal tumour derived from thyroid follicular epithelium, has been found to be sensitised to lenvatinib when CDK2 is targeted via senescence induction." (PMID 41537447, 2026). "Emerging evidence suggests that inhibiting CDK2 can potentiate anti-tumor immunity and synergize with immunotherapy." (PMID 41614894, 2026). "Targeting Aurora Kinase A along with CDK2 inhibition should destabilize spindle dynamics, increasing mitotic errors and eliminating polyploid tumor cells." (PMID 40232858, 2025). "It reduces the expression of cyclin D1, cyclin kinase-dependent kinase 2 (CDK2), cdc2/cyclin B complex, and other cell cycle-related proteins, and blocks tumor cells from G1 / S phase and G2 / M phase, thus exerting an antitumor effect." (PMID 38918994, 2025). "Typically, CDK2 exacerbates tumor progression by regulating cell cycle progression and DNA damage response." (PMID 39944690, 2025). "CDK2 inhibitors enhance anti-tumor immunity by regulating the IFN signaling pathway and improving the tumor immune microenvironment." (PMID 41463246, 2025). "In conclusion, the combination of INX-315 with CDK4/6 inhibitors presents a promising strategy to extend the therapeutic applicability of INX-315 beyond CDK2-addicted tumor types." (PMID 39924553, 2025). "To further determine if the interferon signaling pathway is involved in MTX-mediated anti-tumor effects in Cdk2-/- tumors, we treated C57 mice carrying Cdk2-/- MCA205 tumors with antibodies that neutralize IFNAR1." (PMID 40557162, 2025). "Despite the pronounced antitumor activity of CYC065 and other CDK2 inhibitors, a residual tumor cell population was found to persist after in vivo treatments." (PMID 40232858, 2025). "We analyzed the correlation of CDK2 protein expression with response to lenvatinib in seventeen ATC patients from FUSCC by IHC staining of the tumor samples at initial diagnosis." (PMID 39716890, 2025).
tumor (continued). "In hormone-dependent breast cancer, CDK2 phosphorylates estrogen and progesterone receptors, enhancing their transcriptional activity and thereby driving tumor progression." (PMID 40949156, 2025). "CDK2/7/9 inhibitors induce tumor cell debris, enhancing the therapeutic effect of anti-PD-L1 monoclonal antibodies." (PMID 41463246, 2025). "The staining intensity of Ki67+, p-ERK+, and p-CDK2+ in the island-resident tumor cells was reduced after GDC-0623 treatment, evidence that the drug had on-target effects and reduced tumor cell proliferation." (PMID 40131370, 2025). "Xenograft mouse models demonstrated that both CDK2 knockout and curcumin treatment significantly reduced tumor volumes." (PMID 40469179, 2025). "Compound 17, which exhibited cytotoxicity against PANC−1 cells, was linked to 55 targets, including key targets such as EGFR, AKT1, CDK1, CDK2, MMP9, PIK3CG, and TERT, closely associated with tumour cell proliferation, migration, and apoptosis." (PMID 41006588, 2025). "Type I interferon response plays a crucial role in the effect of CDK2 inhibition combined with MTX treatment, and the anti-tumor effect of MTX plus Cdk2 deletion is related to its kinase activity." (PMID 40557162, 2025). "There are relatively small numbers of tumor models that exhibit strong dependence on CDK2 and undergo G1 cell cycle arrest following CDK2 inhibition." (PMID 39924553, 2025). "It transiently induces the expression of p21, an intracellular inhibitor of cdk2, leading to the dephosphorylation and subsequent inactivation of cdk2, a process that correlates with the suppression of tumor cell proliferation." (PMID 40869085, 2025). "Reprogramming of tumor cells towards kinases such as EGFR, CDK2, and CDK7 has been implicated in resistance to the CDK4/6i palbociclib in ER-positive breast cancer." (PMID 40949156, 2025). "Pharmacophores such as 1,3‐thiazolidin‐4‐ones and bis‐(6‐pyrazolyltriazolo‐thiadiazine) derivatives can effectively inhibit CDK2, providing support for strategies that target dysregulated cell cycle pathways in tumor cells." (PMID 41523619, 2025). "The tumor growth of Cdk2-/- tumor cells overexpressing CD39 is comparable to that of Cdk2-/- tumor cells." (PMID 40557162, 2025). "The deletion of p27 leads to continuous activation of CDK2, jointly propelling rapid cell cycle progression and promoting tumor cell proliferation and survival." (PMID 40438678, 2025). "Ongoing research efforts are focusing on understanding the role of tumor type, co-existing genomic alterations, and aberrant activation of CDK2 as potential biomarkers of response and resistance to CDK4/6 inhibition." (PMID 40317086, 2025). "Given its central role in tumor biology, CDK2 is regarded as a promising therapeutic target, and its targeted degradation is considered an effective treatment strategy 43-45." (PMID 40740234, 2025). "Next, we evaluated the efficacy of the combination of lenvatinib and CDK2 inhibitors in xenograft tumor models of ATC." (PMID 39716890, 2025). "In contrast to the exceptional response, most tumor models demonstrate limited dependence on the CDK2 gene." (PMID 39924553, 2025). "Although an increased expression of ICD-related molecules is observed in vitro, we observe that the tumor growth of Cdk2-/- cells with increased HMGB1 release in Tlr4-/- mice remained similar to that in C57 mice." (PMID 40557162, 2025). "This prompted the development of PF-06873600, the first-in-class selective inhibitor of CDK2/4/6, which has demonstrated antitumor activity as a single agent and in combination with endocrine therapy (ET) in multiple in vivo tumor models." (PMID 40243688, 2025). "LMW-cyclin E1 has been shown to bind more efficiently to CDK2 and to mediate multiple biological processes in tumor progression, such as drug resistance and tumor metastasis." (PMID 40959067, 2025).
tumor (continued). "This compound also transiently upregulates p21, a well-known inhibitor of cdk2, leading to the dephosphorylation and inactivation of cdk2, which correlates with a reduction in tumor cell proliferation." (PMID 40869085, 2025). "Previous studies have shown that cyclin A2 maintains DNA replication by binding to CDK2 to form the CDK2-cyclin A2 complex, which facilitates the S/G2 phase transition and promotes tumor cell proliferation." (PMID 40699652, 2025). "The tumor is distinguished by increased expression in the cyclin-dependent kinase 2 (CDK2) and MDM2 genes on chromosome 12." (PMID 39238675, 2024). "CDK2 is a transcriptional target of MYBL2, which holds true in both NE-like murine tumor models, in which a significant reduction in CDK2 expression occurred in tumors with MYBL2 KO." (PMID 39113611, 2024). "Differential gene expression analysis was performed utilising TCGA-OV RNA-Seq data for 379 samples to analyse genes expressed lower or higher in the tumours with low or high levels of CCNE1 or CDK2 (Q1 vs. Q4)." (PMID 38612869, 2024). "The data suggest that cyclin-E1-overexpressing tumours would be suitable to target using a CDK2 inhibitor." (PMID 38612869, 2024). "In the CDK2 analysis, 449 genes had a higher expression and 1420 genes were expressed less in the tumours with high CDK2." (PMID 38612869, 2024). "CDK2-low-expressing tumours (272 samples, Quartile 1) were compared to CDK2-high-expressing tumours (272 samples, Quartile 4)." (PMID 38732271, 2024). "A comparison of differentially expressed genes was then carried out for CCNE1 and CDK2, where a subset of genes was identified to be altered in the high-expression tumours." (PMID 38612869, 2024). "One of the differentially expressed genes expressed at a higher level in the CCNE1/CDK2-high tumours was FOXA1 (FDR-p value < 0.05; log2 fold changes of 2.2 and 1.1, respectively)." (PMID 38612869, 2024). "According to human data derived from the TCGA and GTEx databases, decreased expressions of miR-4516 and increased expressions of Wnt 8B, DVL3, FOSL1, CCNA1, CCNB1, CDK1, and CDK2 in tumor tissue contributed to the progression of LUAD." (PMID 38930863, 2024). "There were 494 genes that were expressed higher in high-CDK2 tumours, and 10,245 genes were expressed lower in high-CDK2 tumours with a log2 fold change ≥ 1 and FDR p-value < 0.05." (PMID 38732271, 2024). "A previous study has shown that CDK2 inhibitor was more sensitive to inhibit CCNE1-expanded tumor cells." (PMID 38338471, 2024). "Indisulam was first identified as a cell cycle blocker, inhibiting the activation of CDK2 and Cyclin E, decreasing the expression of Cyclin A, Cyclin B1 and CDK2 and arresting tumor cells in G1 phase." (PMID 38593113, 2024). "Numerous studies have underscored the significance of CDK2 in oncogenesis and tumor progression, resulting in a heightened interest in the creation of CDK2 inhibitors as prospective anticancer therapeutics." (PMID 39770509, 2024). "Inhibition of CDK2 can suppress tumor growth and potentially enhance the efficacy of existing treatments." (PMID 38532893, 2024). "In the current study, we have shown that tumours with cyclin E1 and CDK2 overexpression have a worse PFS and OS." (PMID 38612869, 2024). "On the other hand, it can down-regulate the expression of Bcl-2 and CDK-2, thus inhibiting the proliferation of tumor cells." (PMID 39057425, 2024).
tumor (continued). "This novel DNMTI-specific DNA hypomethylation pattern triggers dual inhibition of PI3K-AKT and CDK2-Rb and inactivation of GSK3β, leading to enhanced tumor regression in comparison to that of a PI3K inhibitor." (PMID 38755637, 2024). "The knockdown of TRIM31 reduced the proliferation of GC tumor cells and negatively regulated the cell cycle displayed by the decrease of CylclinD1 and CDK2." (PMID 38978046, 2024). "Genes that were expressed higher or lower in tumours with high CDK2 were identified by pathway analysis." (PMID 38732271, 2024). "Bezafibrate has been demonstrated to inhibit tumor growth by inducing G1 cell cycle arrest through the regulation of CDK2 expression or activity." (PMID 39057711, 2024). "In a subset of tumors, CDK2 inhibition elicits anti-tumor activity by deregulating its regulatory subunits." (PMID 38633613, 2024). "These pathways involve the dual inhibition of PI3K-AKT and CDK2-Rb, along with the inactivation of GSK3β, which regulates reduced cell proliferation and increased cell apoptosis, thus impeding tumor growth." (PMID 38755637, 2024). "It influences genes involved in cell cycle regulation, such as cyclin-dependent kinase 2 (CDK2) and cyclin D1, thereby inhibiting tumour cell growth." (PMID 37628949, 2023). "CDK2 is widely involved in cell cycle progression, which, alongside its regulatory subunits are dysregulated, showing tumor-promoting features." (PMID 37656243, 2023). "In this context, one should also consider that the expression levels of these genes were significantly correlated with tumor grade and that CDK2 was expressed at the highest level in HPV-positive OSCCs." (PMID 36768994, 2023). "The combination of KLK2 and ARA70 can reduce G1 arrest of tumor cells and promote tumor proliferation by regulating p21/cdk2/cyclin D1 signaling pathway." (PMID 37593117, 2023). "FOXD1 binds to the p21 promoter and inhibit its transcription, which inhibits the CDK2/Rb signaling pathway, thus preventing tumor cell senescence and accelerating tumor cell proliferation." (PMID 37563111, 2023). "Apart from promoting in vitro proliferation of GBM cells, CDK2 also facilitates in vivo tumor growth as well as resistance to apoptosis induced by radiotherapy." (PMID 37936247, 2023). "Abnormal expression of CCNE1 activates cyclin-dependent kinase 2 to phosphorylate its substrate, resulting in tumor cell proliferation." (PMID 37404825, 2023). "The main tumor suppressive function originally attributed to CDK2AP1/DOC1 lies in its role as a negative regulator of the cell cycle through the inhibition of cyclin-dependent kinase 2 (CDK2) and DNA polymerase alpha/primase during the S-phase." (PMID 37217493, 2023). "The fundamental role of CDK2 in enhancing tumor cell proliferation has been proved in variety of cancers." (PMID 36720864, 2023). "When treated in combination with etoposide or olaparib, we demonstrated added anti-tumor activity when CDK2 inhibition was sub-efficacious." (PMID 37519629, 2023). "Our findings indicate that HMJ-38 targets BRD4, CDK2, CHEK1/2, and EGFR, which have been implicated in the death of tumor cells and DNA damage pathways." (PMID 38532833, 2023). "Overexpression of cyclin E was previously reported as a mechanism to evade CDK4/6 inhibition because it can activate CDK2 and Rb phosphorylation to re-enter the cell cycle, as observed in preclinical studies and retrospective analyses of tumor tissues." (PMID 36792625, 2023). "Such a mechanism ensures the maintenance of the EGFR/CDK2 signaling axis, which promotes tumor cell proliferation and provides IDH-wt GBM tumor cells with an additional layer of resistance against targeted EGFR/CDK2 inhibition." (PMID 37936247, 2023). "A recent study on murine models found that E2F independent CDK2 inhibition is a critical function required for p107 mediated tumour suppression." (PMID 37667345, 2023).